STAT3 (signal transducer and activator of transcription 3)
Diseases named in the same sentence as STAT3 in open-access papers (continued):
Sharing a sentence is not in itself a finding about the gene and the disease.
prostate carcinoma (continued). "We also investigated the role of signal transducer and activator of transcription 3 (STAT3) in M-HIFU elicited anti-tumor immune response using a transplant tumor model of prostate cancer." (PMID 22911830, 2012). "Stat3 has been shown to induce the metastatic behavior of prostate cancer cells in vitro and in vivo." (PMID 22454635, 2012). "Altogether, these results demonstrate that STAT3 activation can be detected in RM-9 prostate cancer cells in vitro and in vivo, and that M-HIFU reduces the levels of STAT3 activation and STAT3-targeted genes in RM-9 tumors." (PMID 22911830, 2012). "A recent study also indicated that interferon increases the expression of miR-21 and reduces apoptosis of prostate cancer cells through activation of STAT3." (PMID 23272133, 2012). "Among the indirubin derivatives, IDR-E804 has been established as a strong inhibitor of signal transducer and activator of transcription (STAT)-3 signaling in human breast and prostate cancer cells." (PMID 22554053, 2012). "Taken together, our data clearly indicated that the suppression of pro-inflammatory AKT, NF-κB and STAT3 activation plays a role in the inhibition of the progression of prostate cancer in TRAMP mice by UA." (PMID 22427843, 2012). "CT at 7 μM inhibited DU145 prostate cancer cell (STAT3 highly active) growth accompanied by inhibition of STAT3 Tyr705 phosphorylation and the expression of down-stream targets." (PMID 23202971, 2012). "Several studies highlight STAT3 as a valid target for the development of new drugs for prostate cancer and other malignancies." (PMID 21779382, 2011). "Increased JAK/STAT3 and NF-κB activity is expressed in stem cells and tumor initiating stem-like cells in prostate cancer and our findings of active STAT3 and NF-κB in ALDH+ cells is in accordance with this suggestion." (PMID 21779382, 2011). "STAT3 expression is suggested to be correlated to malignant potential and metastatic behavior in prostate cancer." (PMID 21779382, 2011). "This confirms that IL-6 is capable of repressing Necdin expression via STAT3 in prostate cancer cells." (PMID 22046235, 2011). "STAT3 is activated by stimulation of IL-6 which is an important autocrine/paracrine growth factor for prostate cancers and M-110 was shown to interfere with IL-6 induced activation of STAT3." (PMID 22193779, 2011). "In the present study we identified cancer stem cell-like subpopulations in cultured prostate cancer cell lines which responded to treatment with the STAT3 inhibitor galiellalactone." (PMID 21779382, 2011). "Previously, it has been reported that FGF-1 stimulation leads to the activation of ERK1/2, which in turn phosphorylates STAT3 at Ser727 in prostate cancer cells." (PMID 21906308, 2011). "We have shown, both in vivo and in vitro, that the STAT3 inhibitor galiellalactone possesses growth inhibitory effects on prostate cancer cells expressing active, phosphorylated STAT3." (PMID 21779382, 2011). "In the present study, we examined that betulinic acid (BA), a triterpene from the bark of white birch, had the inhibitory effects on hypoxia-mediated activation of STAT3 in androgen independent human prostate cancer PC-3 cells." (PMID 21731766, 2011). "In conclusion, prostate cancer cell lines contained ALDH+ subpopulations with stem cell-like characteristics which expressed phosphorylated STAT3." (PMID 21779382, 2011). "Galiellalactone is a potent and specific inhibitor of STAT3 signaling which has been shown to possess growth inhibitory effects on prostate cancer cells expressing active STAT3." (PMID 21779382, 2011). "Gene expression profiling of prostate cancer stem cells show that the STAT3 signaling pathway is overexpressed in these cells and several studies point to STAT3 as a target for therapeutic intervention in tumor stem cells." (PMID 21779382, 2011).
prostate carcinoma (continued). "In this study we aimed to explore the expression of ALDH as a marker for cancer stem cell-like cells in different human prostate cancer cell lines and the effects of the STAT3 inhibitor galiellalactone on ALDH expressing prostate cancer cells." (PMID 21779382, 2011). "Constitutive STAT3 activation has been found in multiple types of tumors, including melanoma, prostate cancer, head and neck squamous cell carcinoma, and inactivation of STAT3 has been found to inhibit a variety of malignancies." (PMID 20209132, 2010). "For example, RaIA uppregulates VEGF-C in prostate cancer cells during androgen ablation and STAT3 binds to the VEGF promoter and directly regulates VEGF." (PMID 20663134, 2010). "Overall, we demonstrate that SOX1 is an epigenetically regulated target involved in the progression of prostate cancer, and is involved in signaling via the STAT3 pathway." (PMID 20929579, 2010). "Four compounds were synthesized and the most potent of these demonstrated activity similar to STA-21 with an EC50 for apoptosis induction of three Stat3-dependent prostate cancer cell lines with constitutive Stat3 activity ranging from 13.4 to 34.1 μM." (PMID 19274102, 2009). "More research is therefore required to understand the exact mechanisms for activation and translocation of STAT3 to the nucleus and also the consequence of STAT3 phosphorylation in clinical prostate cancer tissue." (PMID 17595657, 2007). "Our study indicating that STAT3 is critical for invasion of prostate cancer cells DU145WT and PC3, secondary to increased cell motility is consistent with these findings and provide for a mechanism by which pSTAT exerts its effects." (PMID 16804520, 2006). "We conclude, based on our findings, that persistently-activated STAT3 is an important molecular marker of prostate cancer, which develops in formerly benign prostate cells and changes their phenotype to one more closely resembling transformed prostate cells." (PMID 15647107, 2005). "We concluded from these experiments that the S3c expressed in BPH-S3c cells was functionally active, and that BPH-S3c cells were dependent upon continued STAT3 expression for their very survival, just like hormone-refractory prostate cancer cell lines." (PMID 15647107, 2005). "There is evidence that STAT3 activation via IL-6 plays a role in the conversion of normal prostate cells to prostate cancer cells, and from androgen-responsive to the androgen insensitive phenotype." (PMID 15647107, 2005). "Moreover, recent studies in prostate cancer models indicate that the STAT3-mediated regulation of SOX genes contributes to cancer cell proliferation and survival, suggesting a broader regulatory mechanism conserved across tissues." (PMID 41511366, 2026). "Investigating the regulatory mechanisms of PRLR and its downstream JAK2/STAT3 signaling axis in prostate cancer may provide a scientific foundation for the development of novel targeted therapies." (PMID 40978029, 2025). "However, clinical application of PRLR and JAK2/STAT3-targeted therapies for prostate cancer is still limited, partly due to severe side effects like immunosuppression and cytotoxicity." (PMID 40978029, 2025). "In prostate cancer, p300‐mediated acetylation of STAT3 at the K685 site stabilises STAT3 dimers." (PMID 39778006, 2025). "This difference may arise from tissue-specific variations, such as distinct genetic backgrounds or differential expression of JAK/STAT3 regulators between prostate cancer and CRC." (PMID 41585878, 2025). "While Osthole might influence other pathways, such as PI3K/AKT, our analysis and experiments emphasize the PRLR - JAK2/STAT3 pathway’s key role in Osthole’s anti - prostate cancer effects." (PMID 40978029, 2025). "Increased expression of Hsp27 modulated STAT3-mediated suppression of apoptosis in prostate cancer." (PMID 41296425, 2025). "It has been shown that STAT3 is involved in the progression of prostate cancer." (PMID 39120316, 2024).
prostate carcinoma (continued). "For instance, STAT3 and STAT5 activation are associated with castration-resistant prostate cancer." (PMID 38339245, 2024). "Therefore, to mitigate the expression of IL-6/JAK/STAT-3 is considered an important target for the treatment of prostate cancer." (PMID 39574470, 2024). "ALT inhibited the STAT3 phosphorylation and signaling pathway in prostate cancer cells after 72 h." (PMID 38397437, 2024). "Of note, IL-6 mediates STAT3 activation and shows unique functions in androgen-dependent prostate cancer progression to the neuroendocrine differentiation stage that is clinically called neuroendocrine prostate cancer, so far, there are no effective therapeutic strategies." (PMID 38245798, 2024). "Moreover, CA suppresses the proliferative markers, and MAPK proteins, and induces apoptosis through inhibiting the IL-6 mediated phosphorylation of JAK/STAT-3 expression in prostate cancer." (PMID 39574470, 2024). "Overexpression of STAT3 has been linked to cancer, and CPT treatment slows the growth of cancer by blocking STAT3 by selectively decreasing STAT3 Tyr705 phosphorylation and its downstream target proteins, which include Bcl-xL, survivin, and cyclin D1 in prostate cancer." (PMID 38397437, 2024). "Indeed, in previous tissue-based studies the ratio of STAT1:STAT3 in tumor cells was highly prognostic in CRC, and in prostate cancer loss of STAT1 associated with increased recurrence." (PMID 38424636, 2024). "We observed that CA could block the IL-6 mediated STAT-3 signaling pathway, leading to apoptosis in prostate cancer cells." (PMID 39574470, 2024). "Cytokines, released by TAMs, can also activate signaling pathways, involved in proliferation and chemotherapy resistance in cancer cells: TAM-derived CCL5 induced activation of signaling pathway STAT3/Nanog in prostate cancer cells, which was related with enhanced resistance to paclitaxel." (PMID 38794298, 2024). "Recent reports have revealed that lipids could promote CRC progression by upregulating β2-adrenergic receptor and toll-like receptor 4 (TLR4) expression and could activate the STAT3 signaling pathway in prostate cancer as a signal transduction mediator." (PMID 38263401, 2024). "Interestingly, most prostate cancer patients exhibit STAT3 expression, and STAT3 activation has been detected in numerous patients with metastatic prostate cancer." (PMID 39161800, 2024). "Hence, STAT-3 overexpression is thought to be a crucial target for the identification of new therapeutical molecules against prostate cancer." (PMID 39574470, 2024). "Furthermore, the activation of STAT3 signaling increases glycolysis, leading to an increase in the growth rate of prostate cancer cells." (PMID 38720012, 2024). "Importantly, the IL‐6/STAT3 signaling pathway has been recognized for its involvement in prostate cancer progression." (PMID 38832957, 2024). "Interestingly, TAMs secrete CCL5 that promotes self‐renewal of prostate cancer stem cells (PCSCs) and enhances migration, invasion, and metastasis of prostate cancer cells by the activation of the β‐catenin/STAT3 signaling pathway." (PMID 38703051, 2024). "However, STAT3 signaling has been recently reported to be responsible for the CSC phenotype in prostate cancer cells." (PMID 37282627, 2023). "Additionally, high SHMT2 expression in prostate cancer has been linkedto a shift in cell metabolism toward anaerobic metabolism by decreasing serine levels and activating STAT3 transcription." (PMID 37108312, 2023). "Finally, it was also shown that activation of STAT3 in the prostate cancer cells while co-culturing with CD4+ cell lines HH and Molt-3 mediated the chemoresistance of prostate cancer cells in response to docetaxel." (PMID 36836690, 2023). "Moreover, MAGI2-AS3 has been shown to inactivate STAT3 signaling and suppress proliferation of prostate cancer cells through acting as a miR-424-5p sponge." (PMID 37025585, 2023).
prostate carcinoma (continued). "Constitutive expression of STAT3 in prostate cancer was correlated with enhanced tumor growth." (PMID 38067351, 2023). "STAT3 is being investigated for its potential involvement in prostate cancer." (PMID 36852795, 2023). "Moreover, PGG markedly inhibited the growth of DU145 prostate cancer tumor xenografts in a mouse model concomitant with the inhibition of phosphorylated STAT3." (PMID 37375411, 2023). "A number of studies in prostate cancer have demonstrated that NDRG1 associates with androgen receptors and inhibits a range of critical signalling pathways, including EGFR, HER2, HER3, PI3K, and STAT3." (PMID 36765657, 2023). "A previous study showed that EHF suppresses STAT3 activation in prostate cancer cells." (PMID 37958443, 2023). "When using CpG-siRNA conjugates that specifically silence STAT3 in TLR9-positive myeloid cells in mouse prostate cancer cells, the downstream STAT3 pathway activation blockage decreased the expression and activity of Arg-1, thus weakening the immunosuppression ability of MDSCs." (PMID 36911674, 2023). "Additionally, lncRNA LINC00893 regulated the suppressor of SOCS3/JAK2/STAT3 pathway by acting as a ceRNA to bind with miR-3173-5p in patient with prostate cancer." (PMID 37620751, 2023). "Targeting miR-375 with e-375i could inhibit prostate cancer cell proliferation, migration, and invasion, and promote cell apoptosis and enzalutamide drug sensitivity in prostate cancer via down-regulating STAT3 expression by up-regulating PTPN4 expression." (PMID 36969009, 2023). "Qi Zhao found LTF could regulate the immune microenvironment of prostate cancer through JAK/STAT3 Pathway." (PMID 36064366, 2022). "NDV can induce CRT membrane translocation, the release of HMGB1, HSP70/90, and ATP in melanoma and prostate cancer cells, which could be enhanced by the STAT3 inhibitor or shRNA‐mediated depletion of STAT3." (PMID 35665592, 2022). "It has been reported that STAT3 may bind to the MALAT1 promoter and transcriptionally stimulate its expression in a model of prostate cancer identifying the IL-8/STAT3/MALAT1 axis as a key regulator during prostate tumorigenesis." (PMID 35814429, 2022). "Enhancing the expression level of STAT3 suppresses autophagy that may promote docetaxel sensitivity of prostate cancer cells." (PMID 35317831, 2022). "Indeed, by investigating the activity of MST2 on STAT3, Tang and colleagues highlighted the effect of the Hippo pathway on prostate cancer through the monomerization of STAT3." (PMID 36555586, 2022). "Accordingly, STAT3 inhibition resulted in a decreased prostate cancer progression in bone and may be responsible for desensitizing prostate cancer cells to chemotherapy." (PMID 35994202, 2022). "In this study, we confirmed that exosomes from prostate cancer cells could induce macrophages to differentiate into the M2 phenotype through the STAT3 signaling pathway." (PMID 35941539, 2022). "For instance, activated STAT3 was believed to be necessary for paclitaxel-induced autophagy due to the addition of IL-6, but acted to inhibit docetaxel-regulated autophagy in castration-resistant prostate cancer cells, leaving the puzzle of how STAT3 affecting autophagy unresolved." (PMID 35690866, 2022). "In present study, we utilized the TAMs/cancer cells co-culture system and proved that QL serum re-programmed the TAMs to M2 phenotype by targeting IL-6/STAT3 signaling pathway, resulting in restoring the sensitivity of paclitaxel-resistant prostate cancer cells to paclitaxel." (PMID 35193986, 2022). "This is supported by the essential role of caveolae in IL‐6‐triggered signaling in multiple myeloma cells, as shown by its abrogation by cholesterol depletion, and by the localization of the IL‐6 receptor and STAT3 protein to the lipid raft compartment in a prostate cancer cell line." (PMID 35451191, 2022).
prostate carcinoma (continued). "Additionally, PGG inhibits STAT3 phosphorylation, resulting in the downregulation of downstream target Bcl-XL and Mcl-1, induces caspase-mediated apoptosis in prostate cancer cells in vitro, and decreases in vivo tumor xenograft growth." (PMID 35890129, 2022). "Using a mouse model of prostate cancer, androgen deprivation has been shown to activate nuclear factor-κB (NF-κB) and STAT3 signaling in prostate cancer cells via leukocyte infiltration, which triggers androgen-dependent tumor cell death and consequently promotes androgen-independent survival." (PMID 36010693, 2022). "Thus, treatment by the simultaneous inhibition of NF-κB and IL-6/STAT3 signaling is a possible therapeutic strategy to improve the response to chemotherapy and radiation in prostate cancer." (PMID 36010693, 2022). "STAT3 mediates TGF-β1-induced Twist1 expression leading to prostate cancer invasion." (PMID 35408745, 2022). "However, LINC00467 favors the higher expression of M2-characteristic genes via the miR-494-3p/STAT3 axis in prostate cancer." (PMID 36117852, 2022). "A similar effect of CAR on STAT3 signaling has also been reported in prostate cancer cells." (PMID 36193062, 2022). "In prostate cancer, stem-like cells were seen to overexpress various genes linked to JAK/STAT signaling pathway, such as IFNK, IFNGR, IL6, CSF2, and STAT1, and stimulate STAT3 to prominently regulate JAK/STAT signaling molecules in mammalian CSC-like cells." (PMID 36359888, 2022). "Higher IL-6 levels result in prostate cancer progression via STAT3 phosphorylation in tumor cells." (PMID 36117852, 2022). "Similarly, in prostate cancer cells, different molecular pathways such as STAT3 (signal transducer and activator of transcription 3) and microRNAs (miRNAs) participate in EMT regulation." (PMID 35317831, 2022). "Moreover, β-caryophyllene oxide has been reported to affect STAT3 signaling, thus resulting in apoptotic cell death and the inhibition of proliferation in multiple melanoma, breast and prostate cancer cell lines." (PMID 35956786, 2022). "Blockade of the STAT3 signaling pathway may induce apoptosis and has been shown to eradicate tumor-initiating cells related to prostate cancer." (PMID 35705962, 2022). "Furthermore, IL-8 has been demonstrated to activate STAT3 signaling in prostate cancer for promoting the disease progression." (PMID 35054486, 2022). "In addition, another tanshinone, cryptotanshinone, was shown to inhibit prostate cancer DU145 cells through the inhibition of STAT3 (signal transducer and activator of transcription 3)." (PMID 35251179, 2022). "Furthermore, UA also inhibited the xenografted prostate cancer in mouse model by inhibiting the activation of STAT3." (PMID 36496432, 2022). "And the CI Extract induces apoptosis by suppressing constitutive STAT3 activation in human prostate cancer DU145 cells, especially the methylene chloride fraction acacetin of CI could inhibit the JAK1/2 and STAT3 signaling pathways." (PMID 35814215, 2022). "Indeed STAT5A/B locus focal amplification was shown to be sufficient to elicit a growth advantage and disease progression in prostate cancer, and similarly here, the STAT3/5 genetic locus was amplified to enhance STAT3/5 expression." (PMID 36341492, 2022). "A neutralizing antibody to IL-6 was found to significantly reduce G6PD expression and STAT3 phosphorylation in prostate cancer cells treated with HS5 CM, demonstrating that bone marrow stromal cell–derived IL-6 can drive up-regulation of G6PD in prostate cancer cells." (PMID 35213227, 2022). "In conclusion, our study shows that exosomes derived from prostate cancer cells can induce macrophages into the M2 subtype by activating the AKT/STAT3 signaling pathway and promote the occurrence and progression of PCa, but this process can be inhibited by GW4869." (PMID 35941539, 2022).